SIGLEC7 (sialic acid binding Ig like lectin 7)
Description:
Putative adhesion molecule that mediates sialic-acid dependent binding to cells. Preferentially binds to alpha-2,3- and alpha-2,6-linked sialic acid. Also binds disialogangliosides (disialogalactosyl globoside, disialyl lactotetraosylceramide and disialyl GalNAc lactotetraoslylceramide). The sialic acid recognition site may be masked by cis interactions with sialic acids on the same cell surface. In the immune response, may act as an inhibitory receptor upon ligand induced tyrosine phosphorylation by recruiting cytoplasmic phosphatase(s) via their SH2 domain(s) that block signal transduction through dephosphorylation of signaling molecules. Mediates inhibition of natural killer cells cytotoxicity. May play a role in hemopoiesis. Inhibits differentiation of CD34+ cell precursors towards myelomonocytic cell lineage and proliferation of leukemic myeloid cells (in vitro).
Synonyms: Siglec-7; AIRM-1; CD328; AIRM1; p75/AIRM1; QA79; CDw328; D-siglec; SIGLEC19P; SIGLECP2; p75
Tractability: Small molecule: a structure with a bound ligand is known; a high-quality ligand is known. Antibody: its Gene Ontology location is reachable by antibodies, with high confidence; UniProt predicts a signal peptide or a membrane-spanning region; the Human Protein Atlas places it where antibodies can reach. PROTAC: its protein half-life has been measured; a small molecule that binds it is known.
Target class: Adhesion
Gene: Protein-coding gene on chromosome 19 (51,142,288 to 51,153,658, forward strand). Ensembl gene ENSG00000168995.
Subcellular location: Membrane
Subcellular location (Human Protein Atlas): Plasma membrane; Vesicles
Pathways (Reactome):
Immune System: Immunoregulatory interactions between a Lymphoid and a non-Lymphoid cell
Gene Ontology:
Molecular function: protein binding; carbohydrate binding; sialic acid binding; signaling receptor activity
Biological process: cell adhesion
Cellular component: plasma membrane; membrane
Genetic constraint (gnomAD): Loss-of-function variants: 33 observed, 42.87 expected, observed/expected ratio (o/e) 0.77, 90% interval 0.58 to 1.03. The upper end of that interval is the gene's LOEUF score, 1.03, which puts it in group 4 of 6, group 1 being the genes least tolerant of losing a copy. Missense variants: 513 observed, 592.84 expected, observed/expected ratio (o/e) 0.87, 90% interval 0.8 to 0.93. Synonymous variants: 242 observed, 247.28 expected, observed/expected ratio (o/e) 0.98, 90% interval 0.88 to 1.09.
Homologues: Orthologues: chimpanzee SIGLEC7 (97% identical), mouse Siglece (53% identical), rat Siglec8 (52% identical), tropical clawed frog siglecl2 (26% identical), tropical clawed frog siglecl2 (24% identical), tropical clawed frog siglecl1 (23% identical), tropical clawed frog siglecl1 (18% identical). Paralogues in human: SIGLEC9 (76% identical), SIGLEC12 (75% identical), SIGLEC8 (72% identical), SIGLEC6 (48% identical), SIGLEC5 (46% identical), CD33 (41% identical), SIGLEC10 (41% identical), SIGLEC14 (41% identical), SIGLEC11 (40% identical), SIGLEC1 (25% identical), MAG (22% identical), SIGLEC16 (19% identical), and 4 more.
Diseases named in the same sentence as SIGLEC7 in open-access papers:
SIGLEC7 is named in the same sentence as 32 diseases in open-access papers, as found by Europe PMC text mining. Sharing a sentence is not in itself a finding about the gene and the disease. The quoted sentences say what the papers report.
breast cancer (4 papers, 2020 to 2025). A primary or metastatic malignant neoplasm involving the breast. "Hypersialylation of tumour antigens has been shown to regulate NK cell function in a Siglec‐7‐dependent manner in both breast cancer (BC) and multiple myeloma (MM)." (PMID 40667828, 2025). "Analysis of the immune cells expressing Siglec‐7 and Siglec‐9 in the breast cancer TME revealed Siglec‐7 expression on CD3+ T cells, CD11b+ myeloid cells and CD56+ NK cells, and Siglec‐9 on CD11b+ cells." (PMID 39246414, 2024). "Analysis of Siglec‐7 and Siglec‐9 expression and function in TN and ER positive breast cancer showed that TN tumors express higher Siglec‐7 and Siglec‐9 RNA and protein levels as compared to ER+ tumors." (PMID 39246414, 2024). "Expression of sialoglycans, including Siglec‐7 and Siglec‐9 ligands, was observed in both TN and ER+ breast cancer tissue sections." (PMID 39246414, 2024). "In this study, we found high Siglec‐7 and Siglec‐9 (ligand) expression in triple negative breast cancer, and to a lower extent in oestrogen receptor positive breast cancer." (PMID 39246414, 2024). "Siglec‐7 expression in the breast cancer TME was found on T cells, myeloid cells and NK cells in human breast tumors, whereas Siglec‐9 was observed on myeloid cells." (PMID 39246414, 2024). "We assessed Siglec‐7 and Siglec‐9 (ligand) expression in TN and ER+ breast cancer tumors and their breast cancer cell line‐induced signalling." (PMID 39246414, 2024). "We therefore hypothesise that Siglec‐7 and Siglec‐9 might be signalling to induce immune cell inhibition in breast cancer." (PMID 39246414, 2024). "Moreover, Siglec‐7 signalling is directly related to Siglec‐7 ligand expression levels of breast cancer cell lines." (PMID 39246414, 2024). "Here we report on the expression of Siglec‐7 and Siglec‐9 and their ligands in TN and ER+ tumors and on Siglec‐7 and Siglec‐9 signalling induced by breast cancer cells to determine their potential as targets for future immunotherapy in breast cancer." (PMID 39246414, 2024). "Moreover, signalling experiments showed Siglec‐7 signalling induced by breast cancer cell lines." (PMID 39246414, 2024). "The influence of Siglec‐7 and Siglec‐9 signalling on TAM polarisation and MDSC function in breast cancer requires more extensive investigation." (PMID 39246414, 2024). "Analysis of the TCGA database showed that the expression of genes HPSE, PIK3AP1, SIGLEC7, LAIR1, and CTSL have positive correlations according to the breast cancer subtypes." (PMID 33053017, 2020). "We therefore envision that immunotherapy targeting Siglec‐7 and/or Siglec‐9 is particularly promising for TN breast cancer patients who do not respond to current treatment options with tumors presenting with high immune cell infiltration." (PMID 39246414, 2024).
cholangiocarcinoma (2 papers, 2020 to 2021). A carcinoma that arises from the intrahepatic biliary tree (intrahepatic cholangiocarcinoma) or from the junction, or adjacent to the junction, of the right and left hepatic ducts (hilar cholangiocarcinoma). "Of notice, while most SIGLEC family genes rarely mutated in cholangiocarcinoma and undifferentiated stomach adenocarcinoma, SIGLEC10 and SIGLEC7 were respectively highly mutated in each of them." (PMID 33240817, 2020).
glioma (2 papers, 2024 to 2025). A benign or malignant brain and spinal cord tumor that arises from glial cells (astrocytes, oligodendrocytes, ependymal cells). "This study explores the close association between SIGLEC7 and the malignant development of glioma, providing a more solid theoretical basis for targeted immunotherapy against SIGLEC7." (PMID 39211050, 2024). "High SIGLEC7 expression predicts poor prognosis in glioma patients and is closely associated with M2 macrophages in the tumor environment." (PMID 39211050, 2024). "In summary, this reveals that high expression of SIGLEC7 is associated with higher malignancy and poorer prognosis in glioma patients." (PMID 39211050, 2024). "Additionally, these results align with our previous findings regarding the association of SIGLEC7 with the malignancy of glioma, further validating that high expression of SIGLEC7 predicts a poorer prognosis for patients." (PMID 39211050, 2024). "We also observed positive correlations between the risk score and several immune checkpoint genes, including SIGLEC7, PDCD1, LILRB2, HAVCR2, and LAG3, which have been tied to poor prognosis in glioma." (PMID 41180518, 2025). "Currently, there is no independent study based on a large number of clinical samples regarding the expression of SIGLEC7 in glioma patients." (PMID 39211050, 2024). "In the future, we look forward to the combination of targeted therapies targeting SIGLEC7 becoming an important strategy for glioma combination therapy, providing more effective treatment options for patients." (PMID 39211050, 2024). "Utilizing immunohistochemistry staining, we investigated the expression of SIGLEC7 in glioma tissues, with results consistent with RNA sequencing data, indicating an enriched expression of SIGLEC7 in higher-grade glioma tissues." (PMID 39211050, 2024). "Based on our research, we can confidently confirm a significant correlation between the expression of SIGLEC7 and poor prognosis in gliomas." (PMID 39211050, 2024). "Our findings revealed a consistent elevation in SIGLEC7 expression across multiple tumor types, notably in LGG and GBM tissues, indicating a potential oncogenic role of SIGLEC7 in gliomas." (PMID 39211050, 2024). "Further analysis by intersecting positively correlated genes from both databases consistently indicated that SIGLEC7 primarily participates in the immune and inflammatory processes of glioma." (PMID 39211050, 2024). "Finally, Cox regression analysis and establishment of survival prediction models proved that high expression of SIGLEC7 is indeed a significant adverse prognostic factor for glioma patients." (PMID 39211050, 2024). "Speculating on the basis of the abundant presence of SIGLEC ligands on tumor cell surfaces, coupled with the inhibitory characteristics demonstrated by numerous SIGLECs, we propose SIGLEC7 as a potentially promising immunotherapeutic target for glioma." (PMID 39211050, 2024). "We speculate that SIGLEC7 may promote glioma progression by upregulating other immune checkpoints and its immunosuppressive characteristics." (PMID 39211050, 2024). "Based on these findings, we speculate that SIGLEC7 predominantly engages in the immune response processes in glioma, consequently influencing its malignant progression." (PMID 39211050, 2024). "Therefore, we comprehensively explored the impact of SIGLEC7 on the expression patterns, biological functions, and prognostic value in glioma patients using the TCGA dataset of 702 cases and the CGGA dataset of 693 cases." (PMID 39211050, 2024). "Considering the significant positive correlation between SIGLEC7 and infiltration of M2 macrophages, we conducted single-cell sequencing analysis of different glioma patient types in the GSE131928, CGGA, and GSE89567 databases to explore their substantive connection." (PMID 39211050, 2024). "Finally, we validated the role of SIGLEC7 in gliomas through tissue and cell experiments." (PMID 39211050, 2024).
glioma (continued). "Therefore, we have reason to believe that the high expression of SIGLEC7 in the mesenchymal subtype of glioma could serve as one of the indicators for diagnosing the mesenchymal subtype of glioma." (PMID 39211050, 2024). "In the future, SIGLEC7 may become a promising target for glioma immunotherapy." (PMID 39211050, 2024). "Combined with our single-cell sequencing analysis showing predominant expression of SIGLEC7 on macrophages, we speculate that SIGLEC7 promotes polarization of M2 macrophages, reshaping the microenvironment, and promoting glioma invasion through the immunosuppressive effect of M2 macrophages." (PMID 39211050, 2024). "Therefore, we hypothesize that SIGLEC7 may exert immunosuppressive effects in glioma." (PMID 39211050, 2024). "Moreover, PAX3 expression demonstrates significant positive correlations with multiple immune checkpoints, particularly PDCD1, SIGLEC7, and LILRB2, underscoring its involvement in immune regulation within the glioma microenvironment." (PMID 41180518, 2025). "To explore the association between SIGLEC7 expression and biological functions in glioma, we conducted Pearson correlation analysis using TCGA and CGGA databases, identifying genes most positively correlated with SIGLEC7 expression (Pearson R > 0.5, p < 0.0001)." (PMID 39211050, 2024). "Contrasting these different groupings in the two datasets revealed that these results were not randomly distributed; notably, SIGLEC7 expression was significantly upregulated in higher-grade gliomas." (PMID 39211050, 2024). "Additionally, SIGLEC7 was highly expressed in IDH wild-type glioma patients, those without 1p/19q co-deletion, and those without MGMT promoter methylation." (PMID 39211050, 2024).
HIV-1 infection (2 papers, 2020 to 2024). The type species of lentivirus and the etiologic agent of acquired immunodeficiency syndrome (AIDS). "Siglec7 is involved in HIV-1 infection, which usually accompanies the changes of Siglec7 expressions on NK cells while maintaining the total number of NK cells in the peripheral blood." (PMID 32322597, 2020). "HIV-1 infection was associated with significant reductions in the production of IFN-γ (P = 0.0264), expression of CD69 (P = 0.0110), and expression of NK cell inhibitory receptor Siglec7 (P = 0.0418)." (PMID 38364104, 2024).
lung carcinoma (2 papers, 2023 to 2024). "Sia-SAMPs (SIGLEC7 and SIGLEC9 ligands) were also upregulated in lung carcinomas compared to healthy tissue." (PMID 39727942, 2024).
osteosarcoma (2 papers, 2020 to 2025). A usually aggressive malignant bone-forming mesenchymal neoplasm, predominantly affecting adolescents and young adults. "Two hub genes, SIGLEC7 and SP140, were positively associated with outcomes in osteosarcoma patients." (PMID 32190007, 2020). "By cross-validation with the GEO dataset, an independent cohort of 42 osteosarcoma cases, we identified two prognostic immune-related genes (Siglec7, SP140) consistent with the Target database." (PMID 32190007, 2020). "Furthermore, the knocking down SIGLEC7 in THP-1 derived macrophages dramatically enhanced their phagocytosis of osteosarcoma cells." (PMID 40756348, 2025). "We confirmed the interaction between GD2 and SIGLEC7 in osteosarcoma by flow cytometry." (PMID 40756348, 2025). "Our study elucidates a hitherto unobserved immune evasion mechanism in osteosarcoma, wherein GD2 engages SIGLECE in mice or SIGLEC7 in human on the surface of macrophage, triggering SHP2-mediated suppression of phagocytic activity." (PMID 40756348, 2025). "While SIGLEC7 has been recognized as the primary GD2 receptor in humans, the lack of a murine homolog introduces uncertainty regarding the extent to which osteosarcoma xenograft models accurately reflect human disease pathology." (PMID 40756348, 2025).
bladder cancer (1 paper, 2024). "SIGLEC7, which belongs to the sialic acid-binding immunoglobulin-like lectins (SIGLECS) family predominantly expressed in leukocytes, has been previously identified as a potential immune checkpoint in bladder cancer." (PMID 38311726, 2024).
breast tumors (1 paper, 2024). "We specifically stained the breast tumor sections for Siglec‐7 and Siglec‐9 ligands using recombinant Siglec proteins, instead of focusing only at general sialoglycan expression." (PMID 39246414, 2024). "Immunohistochemical stainings for Siglec‐7 and Siglec‐9 of nine TN breast tumors and eight ER+ breast tumors were performed." (PMID 39246414, 2024).
colorectal tumor (1 paper, 2024). "Moreover, a recent study has shown that colorectal tumor cells can increase Siglec‐7/9/E ligand expression on stromal cells to induce T cell suppression." (PMID 39246414, 2024).
COVID-19 (1 paper, 2022). A disease caused by infection with severe acute respiratory syndrome coronavirus 2. "SIGLEC6 belongs to the family of sialic acid-binding immunoglobulin-like lectin proteins, out of which SIGLEC1, SIGLEC7 and SIGLEC10 have been implicated to play a role in COVID-19." (PMID 35438176, 2022).
dementia (1 paper, 2022). Loss of intellectual abilities interfering with an individual's social and occupational functions. "The increased dementia risk in individuals with high levels of plasma SVEP1, HE4, CDCP1, SIGLEC‐7, MARCKSL1, CRDL1, or RNAS6 is a novel finding." (PMID 34338426, 2022).
hypospadias (1 paper, 2020). Hypospadias is the displacement of the urethral meatus on the ventrum of the penis. "This region on chromosome 19 is characterized by clusters of sialic acid-binding Ig-like lectin (SIGLEC) and kallikrein (KLK) genes, among which we identified likely causal relationships with hypospadias (CD33/SIGLEC3, SIGLEC5, SIGLEC7, KLK5, KLK7, KLK10, KLK13, and KLK14)." (PMID 32728162, 2020).
liver fibrosis (1 paper, 2023). "A recent report showed that SIGLEC7, released in serum from macrophages, was associated with liver fibrosis and was used as a diagnostic biomarker in patients with MAFLD/MASH." (PMID 38034016, 2023).
melanoma (1 paper, 2023). A malignant, usually aggressive tumor composed of atypical, neoplastic melanocytes. "In this study, we comprehensively analyzed the role of Siglec family genes in melanoma using multiple datasets and found that SIGLEC7 has a mutation frequency as high as 8%." (PMID 37207210, 2023).
mesenchymal tumor (1 paper, 2021). "Interestingly, mesenchymal tumor samples of all cancers, except TGCTs, showed a significantly higher (p < 0.05) expression of SIGLEC7." (PMID 35096592, 2021).
prostate carcinoma (1 paper, 2025). A carcinoma that arises from epithelial cells of the prostate gland. "In prostate cancer, ST3Gal1 was shown to promote immune evasion by synthesizing α2,3‐sialylated ligands for Siglec‐7 and Siglec‐9 receptors on immunosuppressive macrophages, thereby disrupting anti‐tumor immunity." (PMID 40497576, 2025).
prostate tumours (1 paper, 2024). "Transcriptomic analysis of PC patients using camcAPP58 revealed that mRNA levels of both SIGLEC7 and SIGLEC9 are significantly elevated in Gleason grade 9 (4+5) prostate tumours when compared with lower grade tumours." (PMID 38448753, 2024).
Sepsis (1 paper, 2024). Sepsis is defined as life-threatening organ dysfunction caused by a dysregulated host response to infection. "As reported in previous studies, LGALS9 (galectin‐9) exhibited a protective effect in polymicrobial sepsis, SIGLEC7 was an important negative regulator of acute inflammatory responses and was a potential target for the treatment of sepsis." (PMID 39044269, 2024).
steatosis (1 paper, 2023). Increased lipid within the cytoplasm of cells. "Two circulating proteins Sialic Acid Binding Ig-Like Lectin 7 (SIGLETC7) and Dipeptidyl Peptidase 7 (DPP7), also showed significant differences according to the degree of steatosis." (PMID 38034016, 2023).
triple-negative breast carcinoma (1 paper, 2024). An invasive breast carcinoma which is negative for expression of estrogen receptor (ER), progesterone receptor (PR), and human epidermal growth factor receptor 2 (HER2). "Moreover, signalling experiments demonstrated that Siglec‐7 signalling is induced by triple negative breast cancer cell lines." (PMID 39246414, 2024).
virus infection (1 paper, 2020). "Here, we aim to discuss the functions of Siglec7 and Siglec9 in virus infection and tumour progression." (PMID 32322597, 2020). "Although there are abundant evidences that show Siglec7 and Siglec9 expressed on NK cells are related to the HIV, HBV, and HCV infection, the exact mechanism of Siglec7 and Siglec9 involve in these viral infections requires further investigation." (PMID 32322597, 2020). "In this review, we aim to discuss the similarities and differences between Siglec7 and Siglec9 and analyze their functions in virus infection and tumour progression in order to develop better anti-viral and anti-tumor immunotherapy in the future." (PMID 32322597, 2020). "Whereas the most prominent Siglecs of immune regulation on NK cells are Siglec7 and Siglec9, this review will focus on the current research progress on the similarities and differences between Siglec7 and Siglec9 and their functions in tumour and virus infection progression." (PMID 32322597, 2020).